APC (APC regulator of Wnt signaling pathway)
Diseases named in the same sentence as APC in open-access papers (continued):
Sharing a sentence is not in itself a finding about the gene and the disease.
tumor (continued). "has been reported to have a genotoxic effect by suppressing the adenomatous polyposis coli (APC) gene, a tumor suppressor gene thus, increasing the risk of generation and proliferation of cancer." (PMID 37706437, 2023). "The disparity of APC mutations suggests the presence of an alternative mechanism of tumor initiation in CAC." (PMID 37884500, 2023). "Mutations in APC have been identified in early stages of cancer development making it a gatekeeper of tumor progression and therefore an ideal therapeutic target." (PMID 37407577, 2023). "The adenomatous polyposis coli (APC) gene, a tumor-suppressor gene with the encoded protein in the Wnt signaling pathway, was one of the early genetic factors used in the screening of CRC." (PMID 36839042, 2023). "We have recently identified USP7 as a tumor-specific target in CRC carrying APC-truncating mutations." (PMID 36669491, 2023). "Diagnosis has been associated with mutations in DNA nucleotides in tumor promoters such as APC, RAS, and tumor suppressor genes." (PMID 38202898, 2023). "APC is a tumor suppressor gene and its mutations have been correlated to epithelial tumors: GS patients inherit a mutation and, following the “two hits” model, a subsequent additional somatic mutation results in the loss of heterozygosis and tumor development." (PMID 36836031, 2023). "Hyperactivation of TLR-IL1R-mediated Akt-mTOR signaling in SIGIRR-deficient tumors leads to cell cycle progression, loss of heterozygosity of APC, and tumor initiation." (PMID 37869102, 2023). "Conversely, APC/CCDH1 has been associated with a tumour suppressive role as majority of its substrates including SKP2 are known oncoproteins." (PMID 36881608, 2023). "Intraperitoneal (150 mg/kg twice daily) and oral (300 mg/kg twice daily) administration of this drug in mouse xenografts with APC mutations that produce shorter protein forms resulted in 47.2% and 51.9% tumor growth inhibition, respectively." (PMID 37047705, 2023). "Studies also suggest that the mechanism linking abnormalities at the genetic (e.g., APC mutations) and cellular level (e.g., hyperplasia, dysplasia) between tumor initiation to metastasis is the excessive number of colonic CSCs." (PMID 37760539, 2023). "These mutations almost exclusively manifest in the form of truncating mutations in the APC tumor-suppressor gene, preventing the degradation of β-catenin, which leads to uncontrolled proliferation." (PMID 37309673, 2023). "Conversely, overexpression of SREBP2 in the intestine epithelium accelerated tumor growth in APC-mutated tumor models." (PMID 38092754, 2023). "We found, in human cell lines and patients’ tumor lysates, that APC deficiency trended with higher MDR1 but lower MRP1 levels." (PMID 37108784, 2023). "Adenomatous polyposis coli (APC) is a tumor-suppressor gene, and its mutation causes aberrant activation of the Wnt pathway that promotes tumor growth." (PMID 36739585, 2023). "APC encodes a tumor suppressor protein that combines with β‐catenin within the cytoplasm in the form of protein complexes and negatively regulates the β‐catenin and Wnt signaling pathways, thus preventing excessive cell proliferation." (PMID 37096801, 2023). "In colorectal cancer cell lines with APC mutations, the application of JW-74 resulted in the reduction of tumor growth and cell cycle arrest in the G1/S phase." (PMID 37047705, 2023). "APC's association with Wnt signaling pathways is one of the main factors that indicates its importance as a tumor suppressor." (PMID 37901797, 2023).
tumor (continued). "APC mutations are present at the preliminary stages of neoplasia and are majorly linked with the classic tubular adenoma pathway and CIN cancers." (PMID 37345083, 2023). "Adenomatous polyposis coli (APC) mutation is the first step for tumor initiation in MSS CRC, leading to hyperactivation of the WNT signaling pathway." (PMID 36669491, 2023). "APC is a tumor suppressor gene located on chromosome 5q21, encoding a large scaffolding protein with functions in cell cycle regulation, apoptosis, transcription, and cell migration." (PMID 37577746, 2023). "CRC is particularly favorable for the analysis of tumor progression because it gradually accumulates mutations, and in over 85% of the cases the initial driver mutation is in the APC tumor suppressor." (PMID 37902809, 2023). "The APC gene is a well‐known tumour suppressor gene, associated with CTNNB1, with diverse functions, that is cell migration and adhesion." (PMID 36625073, 2023). "This is, 48% of APC wild-type tumours were BRAF mutated in the bevacizumab treatment arm, whereas in the cetuximab treatment arm, only 29% were BRAF mutated (p = 0.13, Fisher’s exact test)." (PMID 37666855, 2023). "Cholesterol supplementation in the diet has been shown to promote tumor development in colitis-associated and APC-inactivated models." (PMID 38092754, 2023). "The APC protein acts as a tumor suppressor and downregulation or loss of function of the APC gene are associated with EC." (PMID 37313172, 2023). "Understanding the direct role of the loss of APC in regulating TICs and how to target them, will be essential in eliminating this highly chemoresistant population to prevent tumor regression." (PMID 37108784, 2023). "In the ‘top–down’ model of CRC heterogeneity involving intestinal SCs (ISCs), tumor initiation would start at the top of the crypt, where APC-mutated cells are observed and spread laterally and downward toward the normal crypt." (PMID 37760539, 2023). "APC encodes an anti-tumor protein that competes with the Wnt signaling pathway and is involved in cell migration, adhesion, and apoptosis." (PMID 37835512, 2023). "Mutations in either the Wnt, β-catenin or APC genes are ‘key’ triggers in the dysregulated proliferation of fibroblasts and the development of these tumours." (PMID 35445926, 2023). "Nuclear β‐catenin is a tumor marker in the intestinal tract because the loss of APC activity triggers the stabilization of β‐catenin which then translocates into the nucleus and alters the expression of numerous genes." (PMID 34245130, 2022). "The genetic mutation profiles characteristic from CRC appear to shape the tumor-associated microbiota, and the combination of a set of bacteria was able to predict the loss of function of specific genes, such as APC and ANKRD36C." (PMID 35392220, 2022). "The results showed that the combination of afatinib and vorinostat significantly inhibited tumor growth in mice transplanted with tumor organoids with APC mutations, and the tumor volume was only 10% of that treatment with FOLFOX chemotherapy." (PMID 35273961, 2022). "Ligand-independent mutations drive downstream activation of the Wnt cascade, through mutational inactivation of APC, the key tumour suppressor gene (80%), or gain-of-function CTNNB1 mutations (<5%) which also result in ligand-independent mutations." (PMID 35815339, 2022). "Previous studies showed that stop-gain mutations of APC deactivate the tumor-suppressor functions of the encoded proteins and confer oncogenic gain-of-function activity, resulting in the rapid development of aggressive carcinoma." (PMID 35459861, 2022). "Mutations of the APC tumor-suppressor gene are thought to regulate beta-catenin within the Wingless/Wnt signal transduction pathway." (PMID 35936696, 2022). "The identification of APC mutations and the establishment of APC as a gatekeeper against tumour formation paved the way for understanding the mutational sequences leading to CRC." (PMID 35736432, 2022).
tumor (continued). "These tumours begin as adenomatous polyps due to the APC gene’s deactivation mutation [encodes the WNT pathway effector adenomatous polyposis coli (APC)]." (PMID 35010119, 2022). "Inactivating the adenomatous polyposis coli (APC) tumour suppression gene through the mutations can activate the Wnt signalling pathway at this stage." (PMID 35846992, 2022). "Even though MSX1 hypermethylation and down-regulation are also reported in colon cancer, Horazna and colleagues point out that MSX1 is overexpressed in colon villous adenomas and takes a crucial role in tumor initiation due to APC loss." (PMID 35486660, 2022). "Other truncating mutations of tumor related genes (APC, BRCA1, EGFR, FLT4, etc) were also decreased rapidly during treatment." (PMID 36341335, 2022). "Adenomatous polyposis coli (APC) is a tumor suppressor gene inhibiting polyp’s formation, which upon mutation causes neoplasia formation causing cancer." (PMID 36250024, 2022). "Among the earliest genetic events in adenoma formation, mutations in the APC tumour suppressor and the KRAS proto-oncogene cause hyperactivation of the pro-proliferative Wnt and MAPK signalling pathways, respectively." (PMID 36477656, 2022). "The treating medical oncologist considered the rectum to be the primary site, because this had the highest FDG-PET avidity, with uptake in perirectal nodes, a nearly obstructing mass seen on sigmoidoscopy, and the presence of APC mutations in the tumor." (PMID 35454817, 2022). "K-Ras mutations alone do not significantly induce the malignant transformation of the mouse intestinal epithelium; however, additional APC mutations synergistically enhance tumor growth and metastasis in the liver and lungs." (PMID 35453609, 2022). "Mechanistically, this occurs as a result of the β-catenin/TCF4 complex binding to the PD-L1 promoter, leading to increased transcription, so that APC mutations can induce tumor immune evasion via an immune checkpoint pathway." (PMID 35937946, 2022). "The reduction in APC protein concentration, caused by chromosomal instability, helps to form tumor since the protein acts as a brake for cell divisions." (PMID 35782078, 2022). "Results showed that circulating tumor cells have not only the same mutated driver genes (such as APC, KRAS, or PIK3CA) with the primary and metastatic lesions but also new variant genes." (PMID 35799608, 2022). "In line with this, CX5461 treatment of organoids established from a patient harboring a germline APC mutation, and two patient‐derived tumor organoids (PDO) showed significant growth inhibition." (PMID 35673898, 2022). "APC is a tumor suppressor gene and exerts its anti-proliferative effects as an antagonist of the Wnt pathway, whereby APC downregulates β-catenin through its association with the APC/Axin/GSK3-β destruction complex." (PMID 35712511, 2022). "The two nonsynonymous somatic variants detected in APC were regarded as minor clonal variants, i.e., present in a subset of tumor cells." (PMID 35205758, 2022). "Two tumor specimens harbored two different mutations for each of the APC and CTNNB1 genes (subjects 6 and 37, respectively)." (PMID 34986841, 2022). "Of the different subtypes of CRC, the most common subgroup (80%) is characterized by causative mutations in the adenomatous polyposis coli (APC) tumor suppressor gene, with the loss of APC initiating tumor development." (PMID 35658010, 2022). "This mechanical strain can be associated to the intestinal transit and, when APC is down regulated, can favor the presence of polyps and tumor growth." (PMID 35454852, 2022).
tumor (continued). "In tumor number 1003, a large deletion was found in one allele of APC, resulting in loss of heterozygosity, whereas the other allele had multiple SVs, including a deletion in the exonic region." (PMID 35343095, 2022). "The mTOR inhibitor rapamycin found in previous studies can inhibit the prolongation of protein translation in APC-deficient tumor cells and can cause tumor cell growth stagnation." (PMID 36258178, 2022). "The wtAPC and APC-mutated primary patient tumor cells were successfully engrafted into nude mice and once established were treated with simvastatin." (PMID 35712511, 2022). "The role of the adenomatous polyposis coli (APC) tumour suppressor mutation in apigenin potential to cause cell cycle arrest was investigated in another study." (PMID 36144783, 2022). "APC is a tumor suppressor gene that encodes a multi-functional protein that is involved in several processes, including regulation of β-catenin/Wnt signalling, intercellular cell adhesion, proliferation, apoptosis and differentiation." (PMID 35439935, 2022). "Another famous tumor suppressor in CRC is APC, whose mutations cause dysregulation of the Wnt/β-catenin pathway, leading to CRC progression." (PMID 35269880, 2022). "MMRd was detected in adjacent normal colorectal mucosa, and in the tumor, mainly somatic frameshift variants in APC were found, which likely result from unrepaired insertion/deletion loops due to MMRd." (PMID 36291559, 2022). "Among the members of the destruction complex, APC is regarded as a CRC tumor suppressor that can be mutated both in the germline and at the somatic level." (PMID 36056393, 2022). "Chr5q22.2 contains the tumor suppressor gene APC, whose deletion or inactivation leads to activation of the Wnt signaling pathway and loss of a tumor-suppressive function." (PMID 35836817, 2022). "The APC gene encodes a multidomain protein that plays a significant role in tumour suppression by negatively regulating the WNT signalling pathway." (PMID 35255942, 2022). "Previous genomic analyses of desmoid tumor profiles have reported the presence of CTNNB1 or APC mutations, but only in a few oncogenic lesions." (PMID 36497457, 2022). "Mutation of the APC gene, a multi-functional tumor-suppressor gene, is an early event in the development of CRC and result in activation of Wnt/β-catenin signaling pathway, which is a key event for epithelial development." (PMID 35723313, 2022). "The gatekeeper concept was first proposed to describe the role of the adenomatous polyposis coli (APC) tumor-suppressor, which is mutated in the early stages of colorectal cancer." (PMID 35626065, 2022). "Most female patients with FAP and PTC also have a RET somatic mutation in addition to APC germline mutations in their tumours." (PMID 35255942, 2022). "In contrast to activating CTNNB1 mutations, which almost always occur as somatic events in the tumor, pathogenic APC mutations frequently are germline events." (PMID 36181537, 2022). "As a result, tumor progression through the APC pathway involves loss of the hormone GUCA2A that suppresses the tumor-suppressing receptor GUCY2C." (PMID 35907803, 2022). "The APC protein is a tumor suppressor that regulates the Wnt pathway, and loss of APC expression is therefore thought to stimulate proliferation in parathyroid cells." (PMID 33269427, 2021).
tumor (continued). "In the present case, the tumor cells showed nuclear expression of β-catenin and an APC mutation at high mutant allele frequencies, indicating the APC mutation as the driver mutation." (PMID 34513702, 2021). "To determine the role of PKM2 in tumour development promoted by APC mutation-induced Wnt/β-catenin signalling activation, we subcutaneously injected APC-mutated SW480 CRC cells stably expressing the control shRNA or PKM2 shRNA into nude mice." (PMID 33071283, 2021). "Evidence of Wnt signaling pathway activation and loss of function of the tumor regulator APC have been shown in colorectal cancers, even in several other cancers such as lung cancer, breast cancer, and HCC, and it is associated with tumor recurrence." (PMID 33628741, 2021). "For example, APC (APC regulator of the WNT signaling pathway) encodes a multidomain protein that plays a crucial role in tumor suppression by antagonizing the WNT signaling pathway." (PMID 34107880, 2021). "Individual loss-of-function mutations in the TAOK1, GDI2, NF1, and APC genes resulted in transformation of immortalized human Schwann cells and tumor formation in a xenograft model." (PMID 33808166, 2021). "One of miR‐125b downstream targets is the tumour suppressor, adenomatous polyposis coli (APC), and loss‐of‐function mutations in APC have been linked to the progression of cancer." (PMID 33332677, 2021). "There was also a direct association between APC promoter hyper methylation and grade of tumor differentiation." (PMID 33883026, 2021). "Warburg effect and growth of xenografted tumours-induced by APC-mutated-CRC cells were suppressed by PKM2-depletion." (PMID 33071283, 2021). "Studies on the causes responsible for the CRC onset have established that it is linked to mutations in APC gene, a classical tumor suppressor gene." (PMID 33672730, 2021). "Another important Wnt antagonist with tumor suppressor activity is the APC gene that is involved in cell migration and adhesion, transcriptional activation, and apoptosis; APC promoter methylation has a diagnostic role in NSCLC." (PMID 34885084, 2021). "R/Z function is of fundamental importance for keeping stem cells in check, as evidenced by double knockout mice which show strong over‐proliferation of the intestinal stem cells and formation of tumours, similar to APC mutations." (PMID 33938624, 2021). "20.8% of CRC cases presented a truncation mutation in APC which is associated with early onset of tumor, advanced stage, and poor prognosis." (PMID 34488905, 2021). "APC loss-of-function allows immortalized human Schwann cells to form a tumor in vivo, most probably because of its cross-talk with the Hippo pathway." (PMID 34445326, 2021). "In our study, POAG relevant CNVRs were found encompassing the APC (Regulator of WNT Signalling Pathway) gene that encodes a tumour suppressor protein." (PMID 34348663, 2021). "After adjusting for age at diagnosis and tumour stage, the association remained consistent for APC (HR = 1.24, 95% CI: 1.04–1.49), TMEM101 (HR = 1.22, 95% CI: 0.99–1.51) and HCG4P3 (HR = 1.25, 95% CI: 0.91–1.72)." (PMID 33461604, 2021).